CCRL2 (C-C motif chemokine receptor like 2)
Diseases named in the same sentence as CCRL2 in open-access papers (continued):
Sharing a sentence is not in itself a finding about the gene and the disease.
tumor (29 papers, 2016 to 2026). "CCRL2 is highly expressed in the tumor microenvironment and various human cancers, and its expression has been linked to delayed tumor growth in mouse models, primarily through the chemerin/CMKLR1 axis." (PMID 40867595, 2025). "The delayed tumor progression observed in Ccrl2 KO mice was associated with a reduction of the recruitment of NK cells, and the involvement of endothelial cells in this phenotype was proposed." (PMID 34638484, 2021). "In the DMBA/TPA model, we cannot exclude a contribution of leucocyte populations, but the higher number of tumors observed in Ccrl2 KO mice might be linked also to changes in the distribution of chemerin in the tumor microenvironment." (PMID 34638484, 2021). "Notably, all six expression-based markers for human TI-Tregs, TIGIT, TNFRSF9, ICOS, CCR8, CD83, and CCRL2, were ranked within the top 10%, which indicates that they are likely to play major roles in tumor-associated Treg functions." (PMID 33598101, 2021). "Similarly, Ccrl2-deficient mice were more permissive for tumor growth following orthotopic injection of a tumor cell line obtained from KrasG12D/+/p53LoxP mice." (PMID 33363177, 2020). "Therefore, we examined whether Ccrl2 deficiency in the host modifies the recruitment of immune cells to the tumor microenvironment." (PMID 34638484, 2021). "CCRL2 exhibits context-dependent roles in cancer, acting as a tumor suppressor in some contexts while promoting tumor progression in others." (PMID 40867595, 2025). "In summary, our study uncovers a novel, cell-autonomous function of CCRL2 in controlling tumor spheroid morphology and inflammatory gene expression." (PMID 40867595, 2025). "The combination of chemerin and CCLR2 induces leukocyte chemotaxis and the expression of CCRL2 in tumor cells can increase the local activity of chemotherapy drugs, inhibit neovascularization, and subsequently inhibit tumor growth." (PMID 40959100, 2025). "Chemerin is an important chemotactic agent that induces immune cell recruitment through its receptors CMKLR1, GPR1, and CCRL2, thereby inhibiting tumor growth." (PMID 40959100, 2025). "These phenotypic differences were consistent across multiple culture conditions, suggesting that CCRL2 intrinsically governs tumor cell organization." (PMID 40867595, 2025). "While CCRL2’s role in immune surveillance is well established, its tumor cell-intrinsic functions remain less clear." (PMID 40867595, 2025). "As tumor cell migration shares many similarities with leukocyte trafficking, we investigated the role of CCRL2 in tumor cell motility." (PMID 40867595, 2025). "On day 15, to ensure balanced baseline tumor burdens, mice were stratified into groups with comparable bioluminescence signals and received anti-CCRL2 ADC or conjugated IgG2a (0.75 mg/kg, one dose)." (PMID 41282192, 2025). "These transcriptomic patterns mirror the observed structural differences between spheroids and suggest a regulatory role for CCRL2 in controlling tumor architecture via transcriptional modulation of adhesion and signaling pathways." (PMID 40867595, 2025). "By differentially modulating the TLR4 and IFN-γ/STAT1 signaling axes, CCRL2 acts as a context-specific regulator of innate immune responses and tumor architecture." (PMID 40867595, 2025). "Here, we investigated the impact of CCRL2 overexpression and knockout on tumor cell behavior in vitro." (PMID 40867595, 2025). "CMKLR1, GPR1, and CCRL2, the primary cellular receptors for chemerin, can be found in both normal and tumor tissues." (PMID 40959100, 2025).
tumor (continued). "Chemerin binds to the receptors CMKLR1, GPR1 or CCRL2 to recruit immune cells, which then regulate the immune inflammatory response of the body and assume antitumor and protumor roles in tumor progression through interactions with different pathways." (PMID 40959100, 2025). "TLR4 on the surface of macrophages interacts with CCRL2 to promote anti-tumor T cell immunity by enhancing TLR4-mediated immune-stimulated macrophage activation." (PMID 39600941, 2024). "CCRL2 was reported to repress tumor growth via suppression of neoangiogenesis and chemerin concentration." (PMID 37274231, 2023). "We also studied the effects of HCLS1, CORO1A and CCRL2 on tumor metastasis-related indicators at the cellular level through in vitro experiments." (PMID 37274231, 2023). "In contrast, other atypical non-G protein signaling chemokine receptors such as CC chemokine-receptor-like 2 (CCRL2), devoid of scavenging properties, can favor anti-tumor responses." (PMID 35159113, 2022). "The modulation of angiogenesis observed in our tumor grafts complements other effects of CCRL2 on the tumor microenvironment observed in other models." (PMID 34638484, 2021). "Ccrl2 KO mice also exhibited a larger number of tumors and faster tumor progression compared to control mice." (PMID 34638484, 2021). "LLC and B16 cells therefore express CCRL2 in vivo, and this expression is likely due to the inflammatory context in the tumor microenvironment, since CCRL2 expression is well known to be strongly upregulated by inflammatory signals in various cell types." (PMID 34638484, 2021). "It is well known that CCRL2 is upregulated in inflammatory conditions, which are frequently present in the tumor microenvironment, and expression of this receptor by tumor cells was reported in several human cancer types." (PMID 34638484, 2021). "CCRL2 expression was moderately affected by the knockout of the host gene, but much more by the knockout of the gene in the tumor cell line." (PMID 34638484, 2021). "B16-CrisprCcrl2 or LLC-CrisprCcrl2 cells generated tumors of similar size in WT and Ccrl2 KO mice, while delayed tumor growth was observed in Ccrl2 KO mice injected with control B16 or control LLC cells." (PMID 34638484, 2021). "Rather, CMKLR1 and GPR1 expression levels vary across many orders of magnitude for most tumor types, while CCRL2 is completely missing from seven of the tested cancer cell lines." (PMID 35008289, 2021). "The results support further that the anti-tumoral effects of CCRL2, when expressed by tumor cells, are mediated by the local concentration of chemerin in the tumor." (PMID 34638484, 2021). "The knockout of Ccrl2 in tumor cells restored the vascularization and necrotic area in Ccrl2 KO mice to a level similar to that observed in WT mice." (PMID 34638484, 2021). "A reduction of neoangiogenesis was observed in tumor grafts expressing CCRL2, mimicking the phenotype of chemerin-expressing tumors." (PMID 34638484, 2021). "Several studies have reported the expression of CCRL2 by tumor cells, and we demonstrated that B16 and LLC cells express CCRL2 in vivo." (PMID 34638484, 2021). "The consequences of CCRL2 overexpression by tumor cells were partially reversed in chemerin KO, Cmklr1 KO, and Gpr1/Cmklr1 double KO mice but unaffected in Gpr1 KO mice." (PMID 34638484, 2021). "All our data support therefore a model in which a higher expression of CCRL2 in tumor cells affects dramatically the distribution of bioactive chemerin, resulting in its concentration in the area (the tumor) in which CCRL2 expression is the highest." (PMID 34638484, 2021). "Delayed tumor growth was also observed when B16 and LLC cells overexpress CCRL2, while knockout of Ccrl2 in tumor cells reversed the consequences of Ccrl2 knockout in the host." (PMID 34638484, 2021). "We show that expression of CCRL2 by tumor cells enhances the local activity of chemerin, which inhibits neoangiogenesis and results in a reduction of tumor growth and progression." (PMID 34638484, 2021).
tumor (continued). "We further investigated the role of CCRL2 on the activity of the chemerin-CMKLR1 axis in tumor progression by testing tumoral cell lines overexpressing CCRL2." (PMID 34638484, 2021). "CCRL2 was highly expressed in individual tumor cell lines from the brain, stomach, pancreas, and breast." (PMID 35008289, 2021). "Overexpression of CCRL2 by tumor cells strongly reduced the growth of B16 and LLC tumors in WT mice." (PMID 34638484, 2021). "We also demonstrated that tumor cells overexpressing CCRL2 can display chemerin on their surface in a stable manner, allowing them to trigger functional responses (calcium mobilization in this case) from cells expressing CMKLR1." (PMID 34638484, 2021). "Since CCRL2 is not expressed by mouse NK cells, but was found expressed by CD31+ cells in the lung of tumor-bearing mice, these results further support the role of CCRL2 expression by endothelial cells in the regulation of NK cell recruitment to the lung." (PMID 33363177, 2020). "Chemerin is an important chemoattractant inducing immunocyte recruitment by its receptors CMKLR1, GPR1 and CCRL2, leading to suppression of tumor growth." (PMID 31370263, 2019). "The data consistently showed that chemerin targeted tumor cells and tumor-associated endothelial cells, the major source of GM-CSF and IL-6, via interaction with CMKLR1 and CCRL2, reducing expression of inflammatory cytokines and inhibiting NF-κB activation." (PMID 30555465, 2018). "Taken together, these results showed that chemerin enhanced CSCC cell migration and promoted tumor growth through chemerin/CMKLR1/CCRL2/GPR1 interactions and subsequent activation of MAPK pathway subtypes." (PMID 30555465, 2018). "In summary, we here uncovered the previously unreported GPR1/CCRL2/Chemerin axis in cSCC tumor cells which - via the interrelated activation of the ERK1/2 and JNK- promotes directed migration and most likely tumor progression." (PMID 27907906, 2016). "Further studies across diverse tumor cell lines and cancer types will be essential to determine whether this CCRL2-driven regulatory mechanism is broadly conserved or contextually restricted." (PMID 40867595, 2025). "Our results suggest that CCRL2 expression may influence cell–cell adhesion, thereby potentially contributing to its role in regulating tumor growth in vivo in graft models." (PMID 40867595, 2025). "Notably, these experiments were conducted in the absence of chemerin and CMKLR1, indicating that the observed effects were independent of the chemerin/CMKLR1 axis and solely attributable to CCRL2 expression in tumor cells." (PMID 40867595, 2025). "Previous studies have explored the impact of CCRL2 expression on various tumor cell lines." (PMID 40867595, 2025). "Moreover, using B16 spheroids as a model of 3D tumor growth, we uncovered a clear role for CCRL2 in modulating spheroid architecture." (PMID 40867595, 2025). "CCRL2 upregulation confers a migratory advantage for the epidermal SCC tumor cells, particularly at the invasive front of the epidermis-dermis junction, facilitating their migration towards the dermis, where a gradient of its high-affinity ligand, Chemerin, is established by senescent fibroblasts." (PMID 37762344, 2023). "Stable overexpression of CCRL2 also inhibited the growth of MDA-MB-231 cells both in vitro and in vivo, suggesting that CCRL2 functions as a tumor suppressor in human BC cells and that its expression may have prognostic significance in human BC." (PMID 37208442, 2023). "Also in this study, tumor cells overexpressing CCRL2 were found to aggregate chemotactic proteins, condensing chemerin on the cell surface, thus promoting activation of CMKLR1-expressing cells." (PMID 35875143, 2022). "We next tested whether tumor angiogenesis was also affected by the overexpression of CCRL2 in tumor cells." (PMID 34638484, 2021).
tumor (continued). "We hypothesized that CCRL2 (over)expressed by tumor cells might increase the local concentration of chemerin in the tumor and enhance the functional response of CMKLR1-expressing cells in the microenvironment." (PMID 34638484, 2021). "In order to validate further the model of chemerin presentation by CCRL2, we could demonstrate the binding of a GFP-chemerin fusion protein on the surface of CCRL2-overexpressing tumor cells by immunofluorescence." (PMID 34638484, 2021). "We also investigated the function of CCRL2 in tumor graft models." (PMID 34638484, 2021). "Altogether, these results show that exclusive or higher CCRL2 expression in tumor cells relative to the host concentrates chemerin locally and inhibits tumor neoangiogenesis, with consequences similar to those resulting from the expression of bioactive chemerin by tumor cells or by the host." (PMID 34638484, 2021). "We next tested whether tumor cells overexpressing CCRL2 could concentrate chemerin on their surface." (PMID 34638484, 2021). "We next investigated the effect of CCRL2 overexpression by tumor cells on tumor growth in vivo." (PMID 34638484, 2021). "The expression level was somewhat higher in LLC tumors than in B16 tumors and unaffected by the genotype of the mice (Ccrl2 KO or WT), demonstrating that the transcripts derive primarily from tumor cells and less from stromal cells of the microenvironment, such as leucocytes or endothelial cells." (PMID 34638484, 2021). "CCRL2 expression was also detected in colorectal cancer, where increased already in the early phase of liver colonization, what suggests involvement of the receptor in tumor metastatic processes." (PMID 32456359, 2020). "Expression of the chemerin receptors ChemR23 and CCRL2 was described in endothelial cells and chemerin was shown to modulate angiogenesis ex vivo and in vivo, which may also influence tumor progression." (PMID 31803622, 2019). "Thus, the involvement of CCRL2 in Chemerin-induced cell migration, as a key step in tumor progression, is still confounding as to different tumor entities." (PMID 27907906, 2016). "Supporting these observations, previous studies have shown that CCRL2 can modulate innate immune signaling via direct interactions with receptors such as TLR4, enhancing its plasma membrane stability and promoting MyD88-dependent NF-κB signaling in tumor-associated macrophages." (PMID 40867595, 2025). "Therefore, we investigated the potential effect of CCRL2 expression by tumor cells on tumor growth." (PMID 34638484, 2021). "Additionally, they also found that deletion of the CCRL2 gene promoted tumor progression." (PMID 33910576, 2021). "Moreover, increased levels of CCRL2 were found in tumor tissues with higher immune infiltration." (PMID 32456359, 2020). "Hence, CCRL2 constitutes the most abundant Chemerin receptor in cSCC cells, suggesting that it may favor the enhanced migration of cSCC tumor cells to invade the Chemerin-rich dermis." (PMID 27907906, 2016). "First, a comprehensive transcriptional analysis of the chemokine receptor expression in cSCC cell lines revealed a remarkable upregulation of CCRL2 in cSCC cell lines compared to normal keratinocytes, a finding which was further confirmed with the immunostaining of patient tumor biopsies." (PMID 27907906, 2016). "In tumors, C–C motif chemokine receptor-like 2 (CCRL2) enhances TLR4-mediated inflammatory signaling by interacting with membrane TLR4, thereby enhancing anti-tumor T cell responses." (PMID 36658573, 2023). "In the present work, we investigate the impact of CCRL2 expression by the host and tumor cells on the chemerin-CMKLR1 axis and its consequences on tumor progression." (PMID 34638484, 2021). "CCRL2 and CMKLR1 are expressed by endothelial cells, and we demonstrated previously that chemerin expression by tumor cells inhibits tumor angiogenesis, thereby promoting cell death and a growth delay." (PMID 34638484, 2021).
tumor (continued). "Chemerin’s main cellular receptors, chemokine-like receptor 1 (CMKLR1), G-protein coupled receptor 1 (GPR1) and C-C chemokine receptor-like 2 (CCRL2) are expressed in most normal and tumor tissues." (PMID 31370263, 2019). "In this study, we investigated the cell-intrinsic role of CCRL2 in tumor cell behavior, independent of its established function in immune surveillance and chemerin/CMKLR1 signaling." (PMID 40867595, 2025). "It is particularly noteworthy that 6 chemokine receptors in GO term “chemokine binding”, including CXCR4, CCR5, CCR1, CCRL2, CMKLR1 and A2M, are specific expressed in FGFR2+ fibrocytes before arriving in tumor sites suggesting their possible roles in fibrocyte recruitment." (PMID 35941662, 2022). "In BC, it may act as a tumor suppressor by recruiting immune effector cells when it is expressed at higher levels in the tumor than in the adjacent healthy tissues, while IL-1β, TNFα, IL-6, and interferon (IFN)γ upregulate CCRL2." (PMID 33670492, 2021). "One significant difference between these models is that Ccrl2 is not knocked out in the tumor cells in the graft models, while it is absent from all cell types in the chemical carcinogenesis paradigm." (PMID 34638484, 2021). "These contrasting results in different tumor models appeared at first puzzling, but it was reasoned that in graft models, the tumor cell lines are not knocked out for Ccrl2." (PMID 34638484, 2021). "Therefore, CCRL2 expression by tumor cell lines does not modify the proliferation rate of B16 and LLC cells in vitro, and the selection of clones did not result in significant changes in the growth pattern of the cells." (PMID 34638484, 2021). "This demonstrated unambiguously that the expression of CCRL2 in tumors could be attributed mostly to tumor cells and not to the microenvironment." (PMID 34638484, 2021). "However, in the absence of CCRL2, active chemerin may leak out of the inflamed tissue much more easily, thereby explaining the faster tumor progression in Ccrl2 KO mice." (PMID 34638484, 2021). "Building on our previous work demonstrating that CCRL2 modulates tumor growth in vivo through the chemerin/CMKLR1 axis, we now show that CCRL2 also influences tumor architecture and inflammatory signaling from within the tumor cells themselves." (PMID 40867595, 2025).